IL10 (interleukin 10)
Diseases named in the same sentence as IL10 in open-access papers (continued):
Sharing a sentence is not in itself a finding about the gene and the disease.
breast tumor (39 papers, 1997 to 2025). "RNA-sequencing of wild-type versus HIF-2α-deficient TAMs in murine breast tumors demonstrated 3 more genes Spint1, IL-10, and Depdc7 were downregulated by HIF-2α knockout and had an identified HIF-2α (not HIF-1α) binding site using previously published ChIP-seq data sets." (PMID 37124241, 2023). "A 2022 study noted that an IL-6/IL-10 mRNA expression signature in breast tumors was paradoxically linked to better survival in early-stage patients, hypothesizing that some level of immune activation (IL-6) combined with IL-10-mediated resolution might be beneficial." (PMID 41007766, 2025). "IL-10 and IL-6 are both known to promote breast tumor growth and are often central to breast tumorigenesis and metastasis." (PMID 38397942, 2024). "Conditioned medium from transduced breast tumor cells contained lower levels of IL-10 and improved the activation of splenic lymphocytes." (PMID 37766222, 2023). "For poorly differentiated breast tumors, an increase in the content of IL-1β, IL-2, IL-6, and IL-10 was observed, while the content of the rest decreased compared to the control group, but to a lesser extent than for highly differentiated tumors." (PMID 36286034, 2022). "IL-10 is a pleiotropic cytokine and has been demonstrated to have both proliferative and inhibitory effect on breast tumor cells." (PMID 36207349, 2022). "The maximum increase in the level of IL-10 is only observed for poorly differentiated breast tumors." (PMID 36286034, 2022). "In another experiment, BMDMs co-incubated with breast tumor cell debris exhibited a robust upregulation of Il10 which is known to stimulate the M2 polarization." (PMID 33809707, 2021). "Another study demonstrated that mice which drank milk fermented with Lactobacillus helveticus R389 had elevated levels of IL-10 and decreased IL-6 levels, both in serum and mammary cells, leading to breast tumour inhibition." (PMID 34201776, 2021). "Many studies have reported the implication of IL-10 in mammary carcinogenesis by revealing the high IL-10 mRNA expression of breast tumor cells." (PMID 30648081, 2018). "Comparatively little is known, however, about the roles of the macrophage-associated cytokines Interleukin-6 (IL-6) and interleukin-10 (IL-10) in the regulation of LVI, and LN metastasis or even their expression in breast tumours." (PMID 29256156, 2018). "Bregs have also been shown to regulate immunity to murine breast tumors independently of IL-10 in vivo and in vitro." (PMID 28507802, 2017). "IL-10 exhibits a complex, multifunctional role, exerting immunosuppressive and antiangiogenic effects while also displaying dual proliferative and inhibitory impacts on breast tumor cells." (PMID 41153842, 2025). "In this study, we examined the changes of ILC1, ILC2, and ILC3 frequency in innate immunity, CD4+ and CD8+ T cells in adoptive immunity, and the expression of their associated cytokines (IFN-γ, IL-4, IL-10, IL-13, and IL-22) in 4T1 and MC4-L2 breast tumor models." (PMID 39877637, 2025). "Due to the direct action of lower exosomal let-7s upon increased CXCLs, IL-6, and IL-10 secretion in BALFs, we believe that the conversion of N2 neutrophils also occurs in the pre-metastatic lung in patients with breast tumor with lower exosomal let-7s." (PMID 35173168, 2022). "In turn, a decrease in IL-10 serum levels will help inhibit breast tumor growth." (PMID 35765486, 2022). "Furthermore, a previous study indicated a potential role of the viral immuno-modulator cytokine IL-10 during HCMV infection in enhancing breast tumor development and metastasis." (PMID 33937031, 2021). "Similarly, we recently identified a suppressive γδ T-cell population that expresses CD73, produces IL-10 and adenosine, and is present in breast tumors." (PMID 32599843, 2020). "Thus, by driving IDO and IL-10 overexpression, breast tumors have the potential to induce an immunosuppressive microenvironment that inhibits the antitumor immune response." (PMID 33679700, 2020).
breast tumor (continued). "Moreover, a subset of murine B220+ CD19+ CD25+ Bregs was shown to be enriched in 4T1 breast tumor-bearing mice and to polarize T cells in culture toward a regulatory T cell (Treg)-like phenotype, again in an IL-10-independent manner." (PMID 28507802, 2017). "In addition, high expression of IL-10 was reported in breast tumors." (PMID 37340387, 2023). "Several plant-derived compounds and natural products have been studied in breast tumors and showed reduction of COX-2, PGE2 and IL-10." (PMID 29609579, 2018). "Significant restrain of colon and breast tumors in mice was induced by delivery of anti-IL-10-receptor antibody in combination with CpG and CCL16, which supported the effectiveness of anti-IL–10 therapy." (PMID 26440936, 2015). "Immunohistochemistry studies show that a majority of breast tumors express IL-10 protein within the tumor microenvironment, whereas normal breast tissue or benign lesions have little to no IL-10." (PMID 41007766, 2025). "The results indicated that the protein levels of IL-10, CD163, and VSIG4 were significantly increased in breast tumor tissues in mice overexpressing HPSE, indicating that HPSE might promote macrophage M2 polarization (CD163, VSIG4) by upregulating IL-10." (PMID 34461608, 2021). "In the model of breast tumor mice, EA significantly reduced the level of inflammatory cytokines including IL-1β and TNF-α and increased the level of the anti-inflammatory cytokine, IL-10, in serum." (PMID 35095910, 2021). "Not surprisingly, IL-10 was found to be highly produced by breast tumors compared to matched normal breast tissue." (PMID 28846716, 2017). "The synchronous elevation of multiple pro-inflammatory and immunosuppressive cytokines, including IL-10 and TGF-β, suggests that breast tumors may establish a paradoxical immune contexture, simultaneously promoting inflammation to support tumor growth and suppressing effective anti-tumor immunity." (PMID 40612845, 2025). "Finally, lower levels of several pro-inflammatory cytokines (IL1B, IL10, IL12, IL6, IL8, TNF), NK cell metagenes (NCR1, XCL1), cytolytic enzymes (GZMA, GZMB, PRF) and type I IFN-induced genes were also observed in IL-1R8 high breast tumors." (PMID 28533483, 2017). "Although the exact mechanism of this IL-10-independent immune suppression is yet unknown, some evidence links Breg activity and CD25+ FoxP3+ T regulatory cell accumulation at tumor sites in murine breast tumors." (PMID 28507802, 2017).
encephalitis (39 papers, 2009 to 2026). An acute inflammatory process affecting the brain parenchyma. "The results suggest that the inflammatory factors with a potential causal relationship with viral encephalitis are artemin, C-C motif chemokine 28, C-X-C motif chemokine 1, interleukin-10 and neurotrophin-3." (PMID 40008261, 2024). "In experimental models, Th2 cytokines (IL-2, IL-4, IL-5, and IL-10) protected JEV-infected mice against viral encephalitis, and high CSF IL-10 levels were associated with protection against brain damage." (PMID 33776990, 2021). "With respect to human virus induced encephalitis, it is also interesting to note IL-10 gene polymorphisms as potential susceptibility factors." (PMID 30619363, 2018). "IL-12p35 suppressed lymphocyte proliferation, antagonized pathogenic Th17 responses, and ameliorated encephalitis in the EAE model by promoting the expansion of Tregs as well as IL-10- and IL-35-producing Breg cells in the brain and spinal cord." (PMID 29051763, 2017). "Similarly, increased IL-10 levels were observed in the serum of patients with other viral encephalitis (HSV), in which it was associated with lower disease severity." (PMID 33776990, 2021). "A combined effect of prolonged exposure to high level of pro-inflammatory cytokines (TNF-α) combined with reduced release of anti-inflammatory cytokines IL-10 and IL-4 in encephalitis conditions may cause immunologic imbalance landed with poor prognosis." (PMID 22276993, 2012). "Compared to HC, patients with encephalitis or encephalopathy presented elevated IL-6 and IL-8 in both serum and CSF, whereas IL-10, IL-1RA, IL-1b and MIG were elevated only in serum, and MCP1 only in CSF (data not shown)." (PMID 35479062, 2022). "The higher CSF concentration of IL-10 in encephalitis patients (n = 294) compared to controls (n = 141) was confirmed by meta-analysis (SMD, 1.31; 95% CI, 0.36–2.26; P < 0.01)." (PMID 36048783, 2022). "According to the analyses, patients with encephalitis had higher CSF amounts of IL-6, IL-8, IL-10, CXCL10, and TNF-α than healthy controls." (PMID 36048783, 2022). "This meta-analysis serves as evidence that encephalitis patients had greater CSF concentrations of IL-6, IL-8, IL-10, CXCL10, and TNF-α when compared to controls." (PMID 36048783, 2022). "Genotype and allele frequencies of IL-1β, IL-4, IL-6, IL-10, and IL-17 in anti-NMDAR encephalitis and control groups." (PMID 33362683, 2020). "In patients with viral encephalitis and controls, we only found significant correlations between OPN and TNF-α (r = 0.632, p = 0.021) in the viral encephalitis patients and IL-10 and TNF-α in the controls (r = 0.617, p = 0.019)." (PMID 33250837, 2020). "Along with TNF-α and IL-2, IL-10 is also a key factor for disease remission from fatal encephalitis due to infection with Oshima strain of Tick born encephalitis virus." (PMID 30619363, 2018). "In a mouse model of coronavirus infection-induced encephalitis, IL-10 produced by CD8+ T cells has been demonstrated to reflect cytotoxic T lymphocytes with a superior effector (cytolytic) function." (PMID 30386336, 2018). "Depletion of G-CSF in GKO mice abolished neutrophil expansion, reinstated IL-10 secretion by T cells, resulting in protection from encephalitis." (PMID 29352287, 2018). "Higher IL-6 and IL-10 levels are frequently measured in several neurological disorders, including encephalitis." (PMID 27538995, 2017). "At the experimental end point (day 31 post-infection) there was a reduction in perivascular cuffing and encephalitis contributing to a significantly improved neuropathology score in IL-10 treated mice." (PMID 26505761, 2015). "Studies evaluating the role of T-cells in the brain during SINV-induced encephalitis have revealed that IL-10 driven responses are protective of the central nervous tissue spaces during infection, as IL-10 suppresses pro-inflammatory stimulation leading to reduced cell death during infection." (PMID 41442410, 2026).
encephalitis (continued). "In a study on experimental autoimmune encephalitis, administering a combination of CBD and THC daily (10 mg/kg, 1:1 ratio), starting 10 days after disease induction, was found to reduce the severity of encephalitis, as indicated by decreased IL-17A and increased interleukin-10 (IL-10)." (PMID 38612615, 2024). "Low levels of IL-10 in the cerebrospinal fluid correlated with more severe encephalitis." (PMID 36674524, 2023). "For instance, βArr2 inhibited the pro-inflammatory cytokines TNF-α and IL-6 and activation of transcription factor NF-κB, increased the expression of anti-inflammatory cytokines IL-10 and IL-4 in microglia for enhancing neurological function in encephalitis mice." (PMID 34787064, 2022). "Similarly, the concentration of the IL-10 in serum/plasma was higher in encephalitis patients (n = 137) than controls (n = 88; SMD, 0.51; 95% CI, 0.21–0.80; P < 0.001)." (PMID 36048783, 2022). "In addition, the serum/plasma levels of the TNF-α were increased in encephalitis patients, but serum/plasma concentration of the IL-6, IL-10, CXCL10, and CXCL13 remained unchanged." (PMID 36048783, 2022). "IL-10 and IL-4, are two cytokines that have been found to have strong links to encephalitis." (PMID 33362683, 2020). "Similarly, a distinct study of encephalitis patients, including a subcohort with HSV-1, revealed that IL-10 levels were associated with a better coma score on admission in the overall cohort." (PMID 30619363, 2018). "Accumulating literature in both rodent models and human encephalitis implicate that manipulation of IL-10 and IFNγ may have broad implications to treat encephalitis more broadly." (PMID 30619363, 2018). "Our studies reveals a novel, complex interplay among IFNγ, G-CSF and IL-10, which highlights the opposing roles of G-CSF and IFNγ in regulation of innate inflammatory responses in a murine viral encephalitis model and reveals G-CSF as a potential therapeutic target." (PMID 29352287, 2018). "The elevated levels of IL-10, IL-6, IL-8, TNFα (cytokines) and CCL2 and CXCL9 (chemokines) in monocytes may help in predicting the pathogenicity of CHPV causing encephalitis and possible entry into the central nervous system." (PMID 27628855, 2016). "Interestingly, brain-infiltrating CD8 T cells produced the cytokine IL-10 in addition to IFN-γ at the peak of BDV-induced encephalitis." (PMID 22114563, 2011). "Elevated IL-10 concentrations in CSF are also reportedly associated with mild encephalitis/encephalopathy during IAV infection with a reversible splenial lesion with a good clinical course, which indicates that IL-10 might work to localize the lesion and to prevent sequelae." (PMID 28912622, 2017). "Through this study, it was confirmed that Caspase 8 levels, Interleukin-10 levels, Interleukin-7 levels, and TNF-beta have a positive correlation on the occurrence of viral encephalitis at the genetic level." (PMID 40008261, 2024). "Our results align with a RVFV encephalitis model using strain CC057 mice, where levels of IL-10, IP-10, IL-6, MIG and MCP-1 were shown to be elevated in plasma on days 5–8 post-infection." (PMID 38140610, 2023). "Nevertheless at 14 dpi, BeAn-infected IFN-β-/- mice showed a stronger encephalitis and astrogliosis, higher viral load as well as higher mRNA levels of Isg15, Eif2ak2 (PKR), Tnfa, Il1b, Il10, Il12 and Ifng in the cerebrum than BeAn-infected WT mice." (PMID 35222374, 2022). "The alteration in the concentration of the different chemokines, such as CXCL10, CXCL-13, CCL-4, CCL-17, CCL-20, and cytokines, including IL-2, IL-4, IL-6, IL-9, IL-10, and IFN-γ have been observed in encephalitis patients." (PMID 36048783, 2022). "This meta-analysis provides evidence for higher CSF concentrations of IL-6, IL-8, IL-10, CXCL10, and TNF-α in encephalitis patients compared to controls." (PMID 36048783, 2022).
encephalitis (continued). "sCD146 levels in the CSF of patients with the acute stage anti-NMDAR encephalitis were significantly increased compared with controls and accompanied by increases in TNF-α, IL-6 and IL-10." (PMID 34220828, 2021). "Significant positive correlations were found between sCD146 levels and IL-10 (r=0.479, p=0.021), IL-6 (r=0.452, p=0.031), and MMP2 (r=0.415, p=0.049) in the CSF of anti-NMDAR encephalitis patients in the acute stage." (PMID 34220828, 2021). "We did not identify any significant differences in SNP genotypes of IL-1β, IL-4, IL-6, IL-10, and IL-17 between anti-NMDAR encephalitis and control groups." (PMID 33362683, 2020). "At the same time, our findings regarding OPN, IL-6, IL-10, and TNF-α raise the question of possible involvement of T cells in anti-NMDAR encephalitis." (PMID 33250837, 2020). "We observed that TNF-α, IL-10, IFN-α, IL-6, CXCL10 and CXCL13 demonstrated >79.1% sensitivity in patients with encephalitis using control 95th centile as cut off (specificity 95%)." (PMID 27575749, 2016). "In our cohort of encephalitis, the Th1 (CXCL10 & TNF-α), T reg (IL-10), B cell (CXCL13) related cytokine/chemokines, and cytokines with broad spectrum of activities including IL-6 and IFN-α, were elevated in more than 75% of the cases." (PMID 27575749, 2016). "In descending order, CSF TNF-α, IL-10, IFN-α, IL-6, CXCL13 and CXCL10 had the best sensitivity (>79.1%) when all encephalitis patients were included." (PMID 27575749, 2016). "Reduced levels of IL-10 in cerebrospinal fluid on days after the onset of encephalitis were observed in patients with encephalitis but not in patients with meningeal disease." (PMID 36674524, 2023). "It has been reported that high levels of cytokines such as IL-1β, IL-6, IL-10, and IFN-γ are correlated with clinical severity in patients with pulmonary oedema and encephalitis, indicating that the immune response of the hSCARB2 mouse model was similar to that of humans." (PMID 34044752, 2021). "IL-2, CXCL10, CCL3, IL-10, CCL22, and IL-6 may represent new biomarkers in patients with anti-NMDAR encephalitis." (PMID 33408682, 2020). "We detected higher levels of TNF-α, IL-10 and GM-CSF in CSF of paraneoplastic anti-NMDARE patients compared to the negative symptom control group (P < 0.05)and lower level of IL-1α and VEGF-A compared to the anti-NMDAR encephalitis patients(P < 0.05)." (PMID 32771066, 2020). "Pronounced effects of IL-10 on pathogenesis and clinical outcome rather than viral control in the CNS are also clearly evident in other viral encephalitis models." (PMID 30619363, 2018). "The presence of IL-10-expressing CD8+ T cells has been reported in several mouse models of infection, including acute influenza infection, chronic Mycobacterium tuberculosis infection, and coronavirus-induced encephalitis." (PMID 28261215, 2017). "Through evaluation of WNV infection in IL-10−/− mice and in wild-type mice that were administered anti-IL-10r mAb or IL-10 neutralizing antibody to temporally block IL-10 signaling, we found that IL-10 signaling facilitates WNV infectivity and lethal encephalitis." (PMID 19816558, 2009). "The analysis showed that there was a statistically significant correlation of CSF cell-free mtDNA with IL-6 (r = 0.307, p = 0.041), but neither with IL-10 (r = −0.085, p = 0.319) nor TNF-α (r = −0.050, p = 0.391) in the acute stage of anti-NMDAR encephalitis." (PMID 30792710, 2019). "Intriguingly, this B cell mechanism appears to be partially IL-10 dependent, since WT but not IL10KO B cells induced complete protection from encephalitis." (PMID 31089128, 2019). "A high CSF level of IL-8 relative to serum levels and elevated levels of IL-10, IFN-gamma, IL-8, tissue regenerating matrix metalloproteinase (MMP)-9, and tissue inhibitor of matrix metalloproteinase (TIMP)-1 were found in encephalitis patients but not in healthy individuals." (PMID 27538995, 2017).